SLC7A1 (solute carrier family 7 member 1)
Diseases named in the same sentence as SLC7A1 in open-access papers (continued):
Sharing a sentence is not in itself a finding about the gene and the disease.
tumor (continued). "We noted a significant correlation between SLC7A1 and CAFs in the TIMER database (P = 0.00015), and immunohistochemical results also suggested that SLC7A1 was highly expressed not only in tumor tissues but also in interstitial tissues in EOC." (PMID 36131790, 2022). "The expression of ADORA2B, SERPINE1 and SLC7A1 was definitely higher in tumor stages III-IV compared with tumor stage I-II (P < 0.05)." (PMID 33828988, 2021). "For example: interferon-gamma (IFNγ) released by CD8+ T cells can down-regulate the expression of SLC3A2 and SLC7A1 in tumor cells, inhibiting the uptake of cystine, limiting tumor development and improving patient prognosis." (PMID 34869390, 2021). "Here we identify, in large cohorts of paediatric tumours, that the arginine transporter SLC7A1 is highly expressed." (PMID 28969007, 2017). "SLC7A1 overexpression of CAFs promoted the invasion and migration of tumor parenchymal cells." (PMID 38752472, 2024). "Next, the effect of SLC7A1 in CAFs on tumor cell migration was examined by scratch assay." (PMID 38752472, 2024). "All tumour types highly expressed SLC7A1 and Arginase, with Arg2 being the main isoform, demonstrating that they could transport and utilise arginine." (PMID 35782058, 2022). "Considering that CCL4 acts as a chemokine, we hypothesized that SLC7A1 is involved in regulating tumor-infiltrating immune cells (TICs)." (PMID 36131790, 2022). "Almost all pHGG tumours showed high levels of expression (>50%) of the arginine transporter SLC7A1." (PMID 35782058, 2022). "In contrast, we observed contradictory effects of LPS including the increased proliferation and expression of several tumor-associated genes and the decreased expression of other cancer-associated genes in tumor enteroids including LOC610994 (Zeta Crystallin), Gpatch4, SLC7A1, ATP13A2, and TEX45." (PMID 35884586, 2022). "While LPS incubation resulted in a pro-cancer gene expression pattern and stimulated proliferation of IBD enteroids and colonoids, downregulation of several cancer-associated genes such as Gpatch4, SLC7A1, ATP13A2, and TEX45 was also observed in tumor enteroids." (PMID 35884586, 2022). "The correlation between prognostic gene expression and tumor stem cell score suggested that ITGA5 and SLC7A1 may have a tumor inhibitory effect, because they were negatively correlated with tumor stemness based on DNAss and RNAss." (PMID 33828988, 2021). "Knockdown of SLC7A1 could significantly inhibit the uptake of arginine in tumor cells." (PMID 41184266, 2025). "In this manuscript, we found that SLC7A1 is also positively expressed in the stroma portion of HGSOC tissue, so as to further investigate whether SLC7A1 in CAFs is involved in the tumor progression of HGSOC, providing a new research idea for the treatment target of HGSOC." (PMID 38752472, 2024). "However, it remains unclear whether SLC7A1 is involved in the amino acid metabolism of OC and the tumor immune microenvironment, and these questions are worthy of further exploration." (PMID 36131790, 2022). "Interestingly, while LPS treatment increased the proliferation and expression of the GEN1, KRIT1, CENPF, CPLANE1, STYK1, and KHDRBS3 genes, it decreased the expression of the cancer associated LOC610994, Gpatch4, SLC7A1, ATP13A2, and TEX45 genes in tumor enteroids." (PMID 35884586, 2022). "Our previous studies have shown that SLC7A1 is highly expressed in EOC cells and is involved in tumor progression, platinum resistance, and amino acid metabolic remodeling in EOC, and is associated with poor progression‐free survival (PFS) in OC patients." (PMID 38752472, 2024). "This is consistent with the absence of proliferation defects upon KD of the major amino acid transporters (SLC1A5, SLC7A1, SLC7A5 and SLC7A11) in K562 tumours." (PMID 38605144, 2024). "SLC7A1 was deposited in the HGSOC matrix, involved in TGF‐β1‐induced CAFs activation and CAFs phenotype acquisition, and promoted tumor cell progression." (PMID 38752472, 2024).
tumor (continued). "Considering that the high expression of CAFs is considered to promote cancer and participates in various biological processes in the tumor microenvironment (TME), the role of SLC7A1 in CAFs is worthy of further study." (PMID 36131790, 2022). "SLC7A1, also known as CAT-1, is highly expressed in some tumor tissues and cells, promoting the occurrence and development of tumors." (PMID 36131790, 2022). "In order to determine which of the three subgroups in MAPK signaling is responsible for the carcinogenic function of SLC7A1, Western blotting results showed that the shSLC7A1 group reduced the phosphorylation of ERK in tumor cells compared with the control group and the shNC group." (PMID 38752472, 2024). "Despite the lack of detection of gene-specific peptides for SLC7A1, SEPepQuant results clearly suggested a pro-tumor role of this gene, which was previously reported in ovarian cancer." (PMID 37726316, 2023). "SLC7A1 not only participates in the metabolic remodelling of free amino acids in EOC cells but also inhibits the expression of the CCL4 molecule, which is closely related to the immune infiltration microenvironment of the tumor." (PMID 36131790, 2022). "We found that increased SLC7A1 expression in EOC cells and tissues was associated with poorer survival outcomes (P < 0.05) but not with tumor stage or grade of OC (P > 0.05)." (PMID 36131790, 2022). "Therefore, our study addressed these problems and found that SLC7A1, a protein highly expressed in EOC, promotes tumor occurrence, development, and drug resistance." (PMID 36131790, 2022). "The fact that MYC controls glutamine uptake and catabolism through transcription of SLC3a2, SLC5A1, SLC7A1, and GLS1 in tumor cells indicates that additional signaling events are involved in determining the target preference of MYC between tumor cells and activated T cells." (PMID 28245597, 2017). "In addition, three members of solute carrier family 7, a family of amino acid transporters, SLC7A1, SLC7A11 and SLC7A6, negatively correlated with miRNA 143–145 cluster, are reported as up-regulated in tumor cells due to the demand for increased amino acid transport during cancer progression." (PMID 23028787, 2012). "However, the role of SLC7A1 in tumor stroma has not been reported." (PMID 38752472, 2024).
cancer (18 papers, 2012 to 2025). A tumor composed of atypical neoplastic, often pleomorphic cells that invade other tissues. "GSEA between the high- and low-SLC7A1 groups revealed significant enrichment of cancer hallmark pathways that are closely associated with cell proliferation, such as the G2M checkpoint, E2F targets, and MYC targets, which were in high accordance with the GSVA at the single-cell level." (PMID 41184266, 2025). "SLC7A1 enriched in cancer‐associated fibroblasts (CAFs) was upregulated by TGF‐β1." (PMID 38752472, 2024). "GSEA based on the cancer hallmark gene sets revealed significant inhibition of E2F targets, MYC targets, G2M checkpoint, Notch signaling, and mitotic spindle pathways in SLC7A1-knockdown IOMM-Lee cells." (PMID 41184266, 2025). "It was further found that SLC7A1 overexpressed in cancer cells participated in TGF‐β1/MAPK signaling pathway, promoting the phosphorylation of Erk MAPK pathway." (PMID 38752472, 2024). "Decreased level of circulating amino acids is linked to increased uptake by cancer cells due to overexpression of amino acid transporters, including SLC1A5 (Gln uptake), SLC1A4 (Ser uptake), SLC7A5 (Leu, Ile, and Val uptake), or SLC7A1 (Arg uptake)." (PMID 38646441, 2024). "CAFs that overexpress SLC7A1 promote invasion, migration, and cell adhesion of cancer cells (SKOV3 and OVCAR3)." (PMID 38752472, 2024). "We used cell adhesion experiments to evaluate the effect of SLC7A1 in CAFs on the ability of cancer cell metastasis, Compared with shNC‐CAFs, shSLC7A1‐CAFs significantly inhibited the adhesion of EOC cells (SKOV3: 716 vs. 398.3, p = 0.0193, OVCAR3:781 vs. 321.3, p < 0.0001)." (PMID 38752472, 2024). "Besides, the presence of CCL4 in NK cells, along with its receptor SLC7A1 in cancer cells, and CCR8 in CD4 + naïve T cells/Treg cells signified an activation of NK cells, which may predict a more favorable pathological response in pCR patients before NAT." (PMID 38566201, 2024). "The different gene effects of SLC7A1, SLC7A2, and SLC7A3 in pan-cancer highlight their distinct molecular functions in tumors, emphasizing the significance of further exploration." (PMID 41184266, 2025). "We found that the cancer patient treatment-relevant relation between PELO and FOCAD, or the experimentally identified interactions between SLC7A2 and SLC7A1, or SLC7A6 and SLC7A1 were best predicted upon combinatorial normalization (Dataset EV1)." (PMID 40263591, 2025). "Like SLC7A1, SLC7A2 is also a cationic amino acid transporter that its function in the regulation of cancer hallmarks is revealed in studies." (PMID 38705513, 2024). "In addition, SLC7A1 may be involved in cancer immune lymphocyte infiltration through CCL4." (PMID 36131790, 2022). "In conclusion, the downregulation of SLC7A1 in EOC cells inhibits the intracellular concentrations of phenylalanine and arginine, thereby affecting the amino acid metabolism of cancer cells." (PMID 36131790, 2022). "The transporters that stand out as potential targets to reduce cancer cell growth are ASCT2 (SLC1A5), LAT1 (SLC7A5), CAT1 (SLC7A1), GC1 (SLC25A22), and SNAT2 (SLC38A2)." (PMID 32859034, 2020). "Furthermore, we analyzed the functional roles of SLC7A1, SLC7A2, and SLC7A3 in pan-cancer using the CRISPR knockout dataset from the DEPMAP portal." (PMID 41184266, 2025). "The results showed that SLC7A1 displayed significantly lower gene effect score compared to SLC7A2 and SLC7A3, suggesting that SLC7A1 plays a more essential biological role in pan-cancer." (PMID 41184266, 2025). "But in contrast to SLC7A1, SLC7A2 expression was found to decrease in various cancer types." (PMID 38705513, 2024). "SLC7A1, also known as CAT‐1, is a cationic amino acid transporter mainly involved in the transport of arginine and lysine, and is highly expressed in a variety of cancer cells to participate in tumor progression." (PMID 38752472, 2024).
cancer (continued). "Similarly, the Kaplan–Meier plots of these cancer patients showed a poor prognosis with higher expression levels of NRF3, SLC36A1, SLC38A9, RagC, each RAB5 isoforms, and SLC7A1 genes." (PMID 36818298, 2023).
infection (4 papers, 2012 to 2023). The state of being infected such as from the introduction of a foreign agent such as serum, vaccine, antigenic substance or organism. "To enable transgene delivery in PVEFs, we therefore infected these cells first with an amphotropic lentivirus encoding Slc7a1 followed by infection with the ecotropic retroviruses separately encoding each of the reprogramming transgenes." (PMID 22675440, 2012). "On the other hand, the Slc7a1 L-arginine transporter was downregulated during the infection, and Nos2, Arg1, Odc1, and Slc7a2 were expressed at similar levels in uninfected macrophages." (PMID 35202090, 2022). "The L. amazonensis macrophage infection decreased the levels of Slc7a1 mRNA after 4 h of infection, and the decreased values were sustained at 24 h, although they were slightly higher than they were at 4 h compared to uninfected macrophages." (PMID 35202090, 2022). "We also observed decreased levels of those miRNAs target genes during infection, such as Cationic amino acid transporters 1 (Cat1/Slc7a1), Cat2/Slc7a22 and Nos2; genes were upregulated in LPS stimuli." (PMID 35202090, 2022). "Although it is rare and less efficient, free viral particles could also be released from infected cells and perform a classic viral cycle of infection mediated by cellular receptors such as AP3D1 or CAT1/SLC7A1 proteins." (PMID 35359744, 2022). "On the other hand, the arginine transporter variant Slc7a1 is a target of miR-410, and miR410-inhibition increased the expression of Slc7a1 after 4 h of infection compared to the negative control." (PMID 35202090, 2022). "PVEFs did not express the receptor (Slc7a1) required for infection with the ecotropic retrovirus used to transduce cells with the reprogramming factors." (PMID 22675440, 2012).
movement disorder (1 paper, 2025). Neurological conditions resulting in abnormal voluntary or involuntary movement, which may impact the speed, fluency, quality and ease of movement. "Recessively inherited cases with consistent neurodevelopmental and movement disorder phenotypes similar to CP were identified for four genes (HSPA12A, SLC7A1, TP53BP1, WWC1)." (PMID 41282771, 2025).
SLC7A1 also shares sentences with these, for which no sentence is quoted: Hypertension (3 papers); adrenocortical carcinoma (1); cardiovascular disease (1); chronic hepatitis B (1); chronic lymphocytic leukemia (1); clear cell renal adenocarcinoma (1); colorectal tumors (1); gestational diabetes (1); glioblastoma (1); hepatitis C (1); Hyperglycemia (1); Insulin resistance (1); mesothelioma (1); metabolic syndrome (1); pancreatic adenocarcinoma (1); renal fibrosis (1); vascular disorder (1).